IL4 (interleukin 4)
Diseases named in the same sentence as IL4 in open-access papers (continued):
Sharing a sentence is not in itself a finding about the gene and the disease.
eosinophilia (continued). "The lack of significant increases in IgE and IL-4 levels in this study also confirms that the eosinophilia by NiO NPs was not produced by the Th2 response." (PMID 27283431, 2016). "In fact, STAT6 knockout mice have no response to IL-4 and IL-13, do not develop Th2 cells in response to IL-4, fail to produce IgE, airway hyperresponsiveness and bronchoalveolar lavage eosinophilia following allergen sensitisation." (PMID 22401596, 2012). "Furthermore, while IL-4/IL-13 signaling through IL-4Rα and STAT6 is essential for AAM protein expression, lung inflammation and eosinophilia are only partially dependent on this pathway." (PMID 22014099, 2011). "Thus it appears that while IL-4/IL-13 signaling through IL-4Rα and STAT6 is essential for induction of AAM genes, lung inflammation and eosinophilia are only partially dependent on this pathway." (PMID 22014099, 2011). "In contrast, overexpression of IL-4 using the CC-10 promoter resulted in baseline eosinophilia without AHR." (PMID 20976014, 2010). "Likewise, biologics against the IL-4 and IL-13 signaling pathways have failed to improve symptoms, although they successfully treat eosinophilia." (PMID 39962262, 2025). "As blocking IL-4 and IL-13 does not influence eosinophil maturation and release from the bone marrow, dupilumab likely traps eosinophils in the blood compartment, which in some patients will manifest eosinophilia." (PMID 40863432, 2025). "The absence of a pronounced effect of BNC on the levels of IL-4, responsible for the activation of B-lymphocytes and humoral immunity, and IL-5, which stimulates eosinophilia, is consistent with the lack of allergenic effect of BNC in the model of systemic anaphylaxis." (PMID 39453014, 2024). "Suppression of eosinophilia was marked, both when Hp‐TGM was given at the time of sensitization, or during repeated challenge, and again we found significant inhibition of eotaxin‐1, IL‐4 and/or IL‐13 responses, depending on the model and the time‐points examined." (PMID 35758054, 2022). "A similar result has been observed in experimental allergic asthma, where the transfer of CCR4+ regulatory T cells obtained from spleens and lymph nodes, but not CCR4− regulatory T cells, attenuates eosinophilia, the production of IL-4 and IL-5, and airway inflammation." (PMID 30584243, 2018). "While eosinophilia and IL-4 expression may be expendable in rodent fibrosis models IL-4 itself is neither particularly elevated in sera, nor in BAL of end-stage IPF patients." (PMID 27677175, 2016). "Indeed, we demonstrated a decrease in the IL-4 levels in 6-month-old mice versus 2-month-old mice, and other studies have shown that treatment of sensitized mice with anti-IL-4 antibody prior to antigen stimulation reduces antigen-induced AHR, eosinophilia, and goblet cell metaplasia." (PMID 24138138, 2013). "Interestingly, we measured substantial increases in IL-4, IL-5, IL-13, and IL-17 from restimulated CD4+ T cells as well as substantial increases in eosinophilia and neutrophilia in the BAL, indicating that our one sensitization model polarizes CD4+ T cells down both Th2 and Th17 pathways." (PMID 20659336, 2010). "Importantly for the development of asthmatic symptoms, the activation of inflammatory Th2 cells through TSLP and their production of the inflammatory cytokines IL-4, IL-5, IL-13 and TNF-α triggers IgE production, eosinophilia, mucus production and fibroblast proliferation." (PMID 18724870, 2008).
eosinophilia (continued). "Interestingly, when systemically administered to mice, IL-25 induces IL-4, IL-5 and IL-13 production from undefined non-T/non-B cells and then induces Th2-type immune responses such as blood eosinophilia and increased serum immunoglobulin E levels." (PMID 18315837, 2008). "The transient eosinophilia did not appear to predict worse clinical outcomes, but it reflects the complex immune modulation when IL-4/IL-13 is blocked, as the latter effect could potentially cause eosinophils to temporarily redistribute from the tissues to blood." (PMID 40843371, 2025). "Based on this observation and the fact that the authors found levels of IL-4 in the hMPV-infected mice to be higher compared to the control, but significantly lower compared to hRSV-infected patients, they suggest that the levels of IL-4 were probably not enough to promote eosinophilia." (PMID 32545470, 2020). "IL-4, IL-5, IL-13, ALOX15, CST1, POSTN, and CCL26 were significantly elevated in patients who had eosinophilia higher than 5%, but not IFN-γ." (PMID 40978168, 2025). "The results revealed that unlike IFN-γ, IL-4, IL-5, IL-13, ALOX15, CST1, POSTN, and CCL26 were significantly elevated in patients with eosinophilia greater than 5%." (PMID 40978168, 2025). "This aspect could explain the absence of blood eosinophilia in COPD and EoE during dupilumab treatment, as the IL‐33/ST2 axis may bypass the effects of IL‐4/IL‐13 inhibition." (PMID 40492692, 2025). "Our findings suggest that eosinophilia, long regarded as central in helminth infections, may be largely dependent on upstream TH2 cytokines, chiefly IL-4, rather than being an independent indicator of infection status." (PMID 40526709, 2025). "Taken together, regardless of the cellular source of IL-4 (Th2 cells, basophils, mast cells and/or eosinophils) increased pulmonary IL-4 levels may, at least partially, account for the lack of effect of rapamycin treatment on AHR and BALF eosinophilia." (PMID 23349887, 2013).
COVID-19 (336 papers, 2020 to 2026). A disease caused by infection with severe acute respiratory syndrome coronavirus 2. "Co-infection also triggered robust increases in IFN-γ and IL-1β, whereas malaria alone was associated with higher IL-6, IL-4, and IL-10, and COVID-19 alone was associated with elevated IL-2 and TNF-α." (PMID 41758897, 2026). "Elevated levels of IL-4 and IL-13, key cytokines associated with AD, have been linked to more severe COVID-19 outcomes." (PMID 40438776, 2025). "Higher concentrations in 2016–17 of IL-8, TNF-α, G-CSF, IL-4, and IL-2R decreased the risk of COVID-19 in 2020–21." (PMID 40910046, 2025). "The release of IL-4 and IL-13 from Th2 cells is considered an important factor for low ventilation and death associated with COVID-19 and these cytokines are targets for immunotherapy agents such as dupilumab." (PMID 39257580, 2024). "Th2 cells from people with PCC presented high capacity to express IL-4 and IL-13, which are related to low ventilation and death associated with COVID-19." (PMID 39257580, 2024). "Of the 105 cytokines profiled in this study, nine were previously reported to be involved in the cytokine storm associated with COVID-19 including the following: IL-2, IL-4, IL-6, IL-10, G-CSF, IP-10, MCP-1, TNF-α, and IFN-γ." (PMID 39062978, 2024). "In detail, systematic reviews and meta-analyses associated the excessive and uncontrolled release of IL-4, IL-8, IL-9, and Eotaxin with more severe COVID-19." (PMID 39125829, 2024). "Proteomics results indicate that microglia and astrocytes in the brains of COVID-19 patients are activated to release inflammatory mediators (IL-4, -6, -12, etc.)causing brain damage." (PMID 36609561, 2023). "IL-6 has been reported to be the leading cause of inflammatory response in severe COVID-19 and emerged as an important regulator of Th1/Th2 differentiation, promoting the IL-4-dependent induction of Th2 differentiation and inhibiting Th1 differentiation." (PMID 37685858, 2023). "The finding that IL-4 associated with severe COVID-19 and associated morality is potentially of high importance and warrants further investigation." (PMID 36211412, 2022). "In moderate COVID-19 patients, the diagnostic performance was fair (acceptable) for IL-Iβ, IL-4, IL-18 and IL-35 because the AUC values ranged between 0.7–0.8." (PMID 36675695, 2022). "These large-scale data revealed that the serum levels of IL-6, IL-10, IL-2R, TNF-α, IL-1β, IL-4, IL-8, and IL-17 are potential risk factors for severity and high mortality in COVID-19." (PMID 35237162, 2022). "We propose that the appearance of GGOs in the CT images of patients with moderate-to-severe COVID-19 is related to increased levels of certain cytokines, and that IL-4 and INF-γ play key roles in causing the cytokine storm and GGOs in these patients." (PMID 33967617, 2021). "Several of these cytokines have been implicated as mediators of COVID-19; for instance, IL-6, IL-4, IL-10 and IFNγ." (PMID 34214142, 2021). "IL-4, as a part of the cytokine storm associated with severe respiratory symptoms, is significantly higher in COVID-19 patients than in healthy individuals." (PMID 34489974, 2021). "Another study confirmed severe COVID-19 patients correlated with increased TNF-α as well as IL-4, where TNF-α was associated with lymphocyte apoptosis and IL-4 interfered with T regulatory cell activity." (PMID 34199761, 2021). "In COVID‐19, the increased amounts of cytokines (e.g. IL‐1β, IFN‐γ, IP‐10, IL‐10 and IL‐4) is associated with COVID-19 severity." (PMID 34118952, 2021). "Studies with patients committed with COVID-19 detected that elevated levels of IL-4 were associated with severe respiratory symptoms." (PMID 35008594, 2021). "COVID-19 patients also show heightened IL-4 and IL-10 levels, cytokines associated with inhibitory inflammatory responses." (PMID 32803199, 2020).
COVID-19 (continued). "In fact, COVID-19-associated male infertility may involve a decrease in testosterone levels and spermatogenesis through shifts in cytokines such as IL-4, IL-6, IFNγ, and TNFα." (PMID 40507130, 2025). "As it is so crucial to understand how to limit inflammation in the response to SARS-CoV-2, we targeted immunoregulatory cytokines transforming growth factor β (TGF-β), IL-10, and IL-4 to assess their roles in pathology in maSARS-CoV-2 infection." (PMID 40854598, 2025). "Balanced IL-4 and IL-5 responses could aid prevent exaggerated inflammation, thus reducing the risk of COVID-19." (PMID 40910046, 2025). "In our study, we described the demographical and clinical characteristics of patients with COVID-19 stratified by severity and assessed associations to infer the potential use of inflammatory cytokines (IL-2, IL-4, IL-6, IL-8, IL-10, TNF-α, GM-CSF, and IFN-γ) as biomarkers of COVID-19 pneumonia." (PMID 40508859, 2025). "In another retrospective analysis using a large COVID-19 international cohort, people who had been receiving treatment for severe asthma with Dupilumab, a monoclonal antibody that blocks IL-13 and IL-4 signalling, demonstrated a lower risk of ventilation and death from COVID-19." (PMID 36851616, 2023). "The increased levels and potential pathogenic effects of IL-4 and IL-13 in AD and COVID-19 suggest that blockades against IL-4/13 may be of some benefit for AD patients infected with SARS-CoV-2." (PMID 37240520, 2023). "In these studies, critical COVID-19 outcomes, extended hospitalization and lymphopenia in COVID-19 patients, and poor prognosis and disease severity were associated with a significant increase in IL-2 cytokine family profile, including IL-2, IL-4, and IL-15." (PMID 37649897, 2023). "Given that IL-4 and IL-13 targeted by dupilumab are Th-2 cytokines, their signaling pathways have not been classically implicated in the cytokine storm typifying severe advanced COVID-19." (PMID 34647194, 2022). "Therefore, post-COVID-19 patients should also benefit from the anti-inflammatory effects of supervised exercise, which is still associated with increased IL-4, IL-10, and decreased chemokines levels." (PMID 36685603, 2022). "A Th2 skew and IL-4 have both been associated with lung damage in COVID-19 patients." (PMID 34214142, 2021). "Overall, CEC attributes of convalescent COVID-19 patients correlated with a vast majority of differentiation and activation factors associated with T cells and B cells (IL-4, IL-5, IL-7, IL-17A, IL-18, MIP-1α, and RANTES), implicating a broad adaptive immune response with endothelial dysfunction." (PMID 33752798, 2021). "In addition, COVID-19 is known to cause a “cytokine storm”, and, in turn, IL-4, involved in brain function (such as memory) and in the beneficial and counteractive role of pro-inflammatory cytokines, remained significantly elevated in all those affected by COVID-19." (PMID 37109156, 2023). "Authors suggested that mast cells may play an important role in triggering the systemic cytokine storm associated with severe COVID-19 because of their production of various mediators, including IL-4 and IL-6, two cytokines involved in COVID-19 disease pathogenesis." (PMID 34685733, 2021). "In our study, IL4 andIL6 were found to be potential biomarkers for predicting the development of coinfection in patients with COVID-19." (PMID 40416960, 2025). "In our dataset, TFH cells showed increased expression of IL21 in convalescent COVID-19 compared with acute disease and control samples, with little IL4 detectable." (PMID 39890933, 2025). "The DEGs shared by RA and COVID-19 mainly involve cell regulated immune responses and IL-4 signaling pathways, further emphasizing the overlap between the two in immune inflammatory mechanisms." (PMID 40495223, 2025).
COVID-19 (continued). "Overall, the data suggest a complex interplay of type 2 cytokines in COVID-19 severity, though little is known about IL-4, as distinct from IL-13, or the kinetics of the 2 cytokines effects in the context of early viremia and longer inflammatory processes." (PMID 40854598, 2025). "The GO terms discovered through DIABLO highlighted a link between Interleukin-4 and Interleukin-13 signaling and COVID-19 severity." (PMID 40429886, 2025). "Dupilumab, an IL-4 and IL-13 inhibitor used in AD treatment, has shown promise in reducing the severity of both AD and COVID-19 by modulating these cytokines." (PMID 40438776, 2025). "Compared with their parents, who were positive for COVID-19, IL-6, IL-4, and IL-12 were modulated (downregulated) by TEN." (PMID 39941142, 2025). "In COVID-19 patients, there’s a marked increase in IL-4 expression and a rise in M2 macrophages, suggesting a significant Th2 immune response and anti-inflammatory activity that potentially leads to airway remodeling." (PMID 38904891, 2025). "In studies related to suppression of cytokine storms in the management of COVID-19, it was found that MSCs-Exo stimulated the release of IL-4, IL-10, and TGF-β." (PMID 40223864, 2025). "Similar patterns have been observed in COVID-19 patients, where elevated levels of IL-4, IL-10, and TNF-α were detected in serum samples." (PMID 41316426, 2025). "Il-13 was recently discovered to be a core driver of COVID-19 severity; patients prescribed Dupliumab, an antibody that blocks IL-13 and Il-4, have significantly less severe disease." (PMID 40429886, 2025). "Studies have indicated that patients with severe COVID-19 exhibit elevated levels of pro-inflammatory cytokines (IL-6, tumor necrosis factor-α) and anti-inflammatory cytokines (IL-4, IL-10), along with decreased expression of CD4 and CD8 cells." (PMID 39040601, 2024). "We found that the NfL levels are significantly predicted by a panel of circulating cytokines/chemokines, including CRP, IL-4, IL-8, IL-9, Eotaxin, and MIP-1ß, which are highly up-regulated during COVID-19 and are associated with clinical outcomes." (PMID 39125829, 2024). "Regarding the anti-inflammatory cytokines, IL-1 receptor antagonists (IL-1Ra), IL-10, and IL-4 significantly increased across the different groups (mild, moderate, and severe) of COVID-19 patients." (PMID 38855114, 2024). "Another study also demonstrated that increased IL-4 expression was correlated not only with mortality but also with the development of respiratory failure and acute renal failure in COVID-19 patients." (PMID 39408907, 2024). "The literature varies on reports on IL-4 expression during COVID-19, similar to the observations for IFN-γ." (PMID 39408907, 2024). "Our study particularly focused on the concentration of anti-inflammatory cytokines (IL-4, IL-10) in the appendixes of children with COVID-19." (PMID 38397914, 2024). "Using the REAC pathway analysis of differentially expressed genes in COVID-19-positive cases, we detected interleukin IL-2, IL-7, and IL-10 as well as IL-1, IL-4, IL-13, and IL-36." (PMID 38240884, 2024). "Evaluate the state of the cytokine balance in the tissues of the appendixes of children of selected age groups with COVID-19 based on the levels of expression of pro-inflammatory (IL-1, IL-6) and anti-inflammatory (IL-4, IL-10) markers." (PMID 38397914, 2024). "Maternal samples were positive in PC2, defined by significant contribution from IP10 (CXCL10) and IL4, factors that have been previously identified as serum biomarkers of COVID-19 severity." (PMID 39845965, 2024). "Moreover, it was reported that epithelial surface bound ACE2 expression is inversely associated with the levels of Th2 cytokines (IL-4, IL-5, and IL-13) that could alleviate the viral-induced release of interferons and downregulate the cytokine storm typical of increasing COVID-19 severity." (PMID 38263182, 2024).